LINC00111 (long independently transcribed non-coding RNA 111)
Synonyms: formerly C21orf21; NCRNA00111
Gene: Long non-coding RNA gene on chromosome 21 (41,679,181 to 41,697,336, forward strand). Ensembl gene ENSG00000227702.
Diseases named in the same sentence as LINC00111 in open-access papers:
LINC00111 is named in the same sentence as 3 diseases in open-access papers, as found by Europe PMC text mining. Sharing a sentence is not in itself a finding about the gene and the disease. The quoted sentences say what the papers report.
cancer (1 paper, 2022). A tumor composed of atypical neoplastic, often pleomorphic cells that invade other tissues. "Taken as a whole, these results demonstrated that LINC00111 possesses tumour-suppressive properties by regulating both TBX2 and p21WAF1/CIP1 expression, and as such has important ramifications for cancer cell survival when targeted for repression by the TBX2-CoREST complex." (PMID 35687133, 2022).
LINC00111 also shares sentences with these, for which no sentence is quoted: breast carcinoma (1 paper); tumours (1).